SDHB (succinate dehydrogenase complex iron sulfur subunit B)
Diseases named in the same sentence as SDHB in open-access papers (continued):
Sharing a sentence is not in itself a finding about the gene and the disease.
tumor (continued). "The tumour cells were also positive for GATA3, E-cadherin, Pax-8, Succinate dehydrogenase B (SDHB) and Fumarate hydratase (FH), and negative for vimentin, Carbonic anhydrase 9 (CA9), CD10, P504s, CK20, TFE3, TFEB, HMB45, ALK and Forkhead box protein I1 (FOXI1)." (PMID 36816543, 2023). "Hence, we aimed to retrospectively collect pathologically identified PPGL tumor tissues from our center and investigate the expression of apelin and SUCLG2 along with previously studied ERBB-2, CNTN4, CHGB, and SDHB in metastatic and non-metastatic PPGLs." (PMID 35574028, 2022). "In syndromic cases, the morphology of the tumor(s), molecular immunohistochemistry (e.g., PTEN, beta-catenin, SDHB), the findings in the non-tumorous thyroid parenchyma, and other associated lesions may provide insight into the underlying disorder." (PMID 33495912, 2021). "All the five tumours in this study had a typical immunophenotype characterized by diffuse positivity for CK7 and negativity for CD117, and were also positive for PAX-8, E-cadherin, FH and SDHB, but negative for vimentin, CD10, P504s, CA9, CK20, TFE3, TFEB, HMB45, and ALK." (PMID 36816543, 2023).
cancer (111 papers, 2010 to 2026). A tumor composed of atypical neoplastic, often pleomorphic cells that invade other tissues. "Appropriate surveillance of SDHB variant carriers is associated with reduced mortality from these cancers." (PMID 41697738, 2026). "Mitochondrial HSP90 homolog TRAP1, but not cytosolic HSP90, binds and stabilizes succinate dehydrogenase-B (SDHB) contributing to HIF-1α-mediated cancer progression in patients carrying SDHB mutations." (PMID 39148727, 2024). "It is reported that SDHB depletion in cancer cells causes succinate accumulation and activation of several oncogenic signalling pathways." (PMID 36717552, 2023). "SDHB deficiency (in terms of expression or activity) has been found in several types of cancer and stimulates cancer progression through energy metabolism reprogramming, succinate accumulation or an increase in reactive oxygen species (ROS)." (PMID 36717552, 2023). "Cellular metabolism and redox balance were found to be altered by the functional disruption of mitochondrial complex II brought on by SDHB mutations in cancer cells." (PMID 37840772, 2023). "The linked nature of SDH and CI was also revealed by reciprocal experiments where either SDHB was knocked out in wild type cells or restored in cancer cells arising from SDHB mutations." (PMID 36883551, 2023). "Silencing of cancer cell SDHB was reported to result in loss of SDH activity and a change in cancer cell behavior; cells are more migratory and exhibit epithelial mesenchymal transition (EMT)." (PMID 37446354, 2023). "Of the hereditary cases, 9% had malignant tumors and these were commonly associated with mutated SDHB." (PMID 36685941, 2022). "Of the 12 known PPGL susceptibility genes included in the multigene cancer panel used in the Hereditary Cancer Program, only SDHB and VHL were mutated." (PMID 36685941, 2022). "In this study, we showed that SDHB deficient cancer cells exhibit a switch in the cellular metabolism from glycolysis to glutaminolysis to survive." (PMID 35008989, 2022). "Upon confirmation of a pathogenic SDHB variant in him, his cancer-free mother, aged 42, underwent cascade testing and was confirmed to carry the same variant, providing evidence of the maternal origin of the variant." (PMID 33308260, 2020). "Early studies linked SDH complex dysfunction with cancer, evidenced specifically by studies that showed that SDHB, SDHC, and SDHD mutations increased superoxide anion release (oxidative damage) which led to cells undergoing apoptosis or transformation." (PMID 33153035, 2020). "Expression of CIIlow complex in SDHB-deficient cancer cells was associated with a decrease in de novo pyrimidine synthesis and cell proliferation along with an upregulation of catabolic and salvage pathways." (PMID 32575796, 2020). "For instance, mutations in SDH subunit B (SDHB) induce the most epigenetic silencing in cancer cells, increasing cell migration and potentially explaining malignancy." (PMID 33171762, 2020). "Cancer-associated SDHB mutations have been found to result in the functional disruption of mitochondrial complex II, which causes catastrophic changes to cellular metabolism and redox homeostasis." (PMID 31979226, 2020). "Although mutations in all subunits occur in cancer, tumors containing mutations in the catalytic subunit SDHB are predominantly malignant and associated with enhanced risk of metastasis." (PMID 31372201, 2019). "Mutations in or downregulation of the SDHB subunit have previously been associated with TGFβ-induced EMT in cancer cells." (PMID 31164982, 2019). "SDH defects are associated with mitochondrial disorders and risk for various cancers; immunochemical analysis indicated loss of SDHB protein expression in the patient’s tumor, compatible with SDH deficiency." (PMID 30680959, 2019). "It would be useful to further investigate the precise mechanism of action of BET inhibitors in the growth suppression of SDHB-deficient cancer." (PMID 28423651, 2017).
cancer (continued). "In this study, we showed SDHB-deficient cancer cells exhibit a switch in cellular metabolism, from oxidative phosphorylation to glycolysis, to adapt for survival." (PMID 28423651, 2017). "In conclusion, we elucidated the metabolic properties of SDHB-deficient cancer cells and found dependence on glycolysis and glutaminolysis for growth." (PMID 28423651, 2017). "Genetic evaluation of other family members for SDHB mutations is in progress, along with genetic counseling regarding the implications of the patient's identified cancer syndrome." (PMID 25215250, 2014). "Notably, genes such as NCOA1 and SDHB are identified as being associated with cancer susceptibility." (PMID 40724918, 2025). "Malignant tumors occur in 5% of SDHD variant carriers compared to 33% in SDHB variant carriers." (PMID 38473347, 2024). "More studies on tumors, patients, and families are needed to inform whether SDHA pathogenic variants are associated with a specific cancer risk profile compared with SDHB, SDHD, or SDHC." (PMID 38885448, 2024). "Glutamine metabolism has been shown to be upregulated in SDHB mutated cancers." (PMID 33153035, 2020). "The expression of such a CIIlow complex may thus result from the metabolic adaptation of SDHB-deficient cancer cells, which are less proliferative, but endowed with high invasive and metastatic capacities." (PMID 32575796, 2020). "We hypothesize that the Arg230His SDHB mutation rewires metabolism, reminiscent of metabolic reprogramming in cancer." (PMID 32859697, 2020). "Currently, however, the characteristics of SDHB-deficient cancers are not completely understood." (PMID 28423651, 2017). "BET inhibitors may be promising therapeutic agents for SDHB-deficient cancers." (PMID 28423651, 2017). "Therefore, drugs that suppress progression of cancer with an SDHB deficiency could fulfill an unmet medical need." (PMID 28423651, 2017). "Studies exploring the role of other SDH subunits in cancer showed that patients with higher expression of SDHB displayed a worse OS than patients with reduced SDHB expression in renal carcinoma." (PMID 40563592, 2025). "Previous studies have demonstrated that the downregulation of SDHB can enhance aerobic glycolysis in various cancer types." (PMID 41339318, 2025). "To test these effects genetically, we used CRISPR/Cas9 to generate gene knockouts (KO) of SDHB, the most frequently mutated subunit in SDH-null human cancers." (PMID 36883551, 2023). "For each cell line, averaged sensitivity profiles to shRNAs targeting GPT or GPT2 were correlated to SDHB expression data from the Cancer Cell Line Encyclopedia (CCLE)." (PMID 37414778, 2023). "After assessing SDHs differential expression in pan-cancer, we found that SDHB, SDHC, and SDHD benefit COAD patients." (PMID 36949947, 2023). "Silencing of SDHB in cancer cells with selective siRNA results in phenotypic changes characterized by enhanced migration and invasion, epithelial mesenchymal transition (EMT) and metabolic switch to glycolysis." (PMID 36344992, 2022). "Cancer cells often present with reduced expression of SDH subunits notably SDHB or SDHD resulting in succinate accumulation." (PMID 36344992, 2022). "We also identified medically actionable variants in eight other cancer-related SFs genes, including APC, MAX, MSH6, MLH1, PALB2, PMS2, SDHB, and TSC2." (PMID 36143288, 2022). "Mutation of SDH subunits (SDHD and SDHB) in hereditary tumors such as paraganglioma or reduction of SDHB expression in cancer results in matrix succinate accumulation which is transported to cytoplasma and secreted into the extracellular milieu." (PMID 36344992, 2022). "In particular, inhibition of SDHB induces the transition to anaerobic metabolism, better known as the Warburg effect, which is widely observed in human cancers." (PMID 37066112, 2022).
cancer (continued). "Even though it was reported that some cancer cells can harbor mutations in all SDH subunits, the most commonly found is a loss of function mutation in the Fe-S cluster of the catalytic subunit SDHB, which is highly associated to malignancy." (PMID 33917317, 2021). "In addition to PPGLs, other malignant tumors may be seen in cases with SDHB mutation." (PMID 34181326, 2021). "Cancer predisposition associated with SDHB germline mutation in PPGL patients is well known, however somatic SDHB mutation had been rarely reported." (PMID 34069252, 2021). "Hereditary PCC accounts for ~35% of cases and has been associated with germline mutations in several cancer susceptibility genes (e.g., KIF1B, SDHB, VHL, SDHD, RET)." (PMID 32354376, 2020). "We successfully detected SDHB and TFE3 mutations in tissues specimens from SDHD RCC and tRCC patients using the pan-cancer panel analysis." (PMID 32811483, 2020). "The variants found in four of the cancer genes APC, BRCA1, RET, and SDHB in our AJ centenarian sample had also been labeled as “almost certainly benign” in another sequencing study (ClinSeq) of 572 middle aged participants (17% of which are of AJ ancestry)." (PMID 25333069, 2014). "In comparison to normal tissue and hyperplasia a significantly (p < 0.05) increased expression of IGF-R1β, GLUT-1, HK 2, TKTL1, LDHA, SDHA, SDHB, and ATP synthase was observed in cancer cells of OSCC." (PMID 25048361, 2014). "It was suggested that SDHB silencing up-regulated HIF-1α via activation of AMPKα in cancers in accordance with the aerobic glycolysis (Warburg effect)." (PMID 25491408, 2014). "And SDHB was proved to be decreased due to upregulation of HIF-1α expression in CoCl2-treated cancer cells." (PMID 25491408, 2014). "Further, HIF-1α and p-AMPKα were found to be upregulated in SDHB-silenced, but downregulated in SDHB-overexpressed cancer cells." (PMID 25491408, 2014). "SDHB, FGFR2 and MUTYH (AUC = 0.68, 0.67 and 0.65, respectively) were similarly associated with diverse cancer types and thus highly variable phenotypes." (PMID 23921638, 2013). "The low SDHB expression might also be influencing neuronal cellular metabolism, as its knock-out in cancer cells diverts metabolism toward glutamate catabolism and glycolysis." (PMID 40585892, 2025). "Succinate accumulation in ccRC with decreased SDHD or SDHB expression was reported to enhance cancer cell invasion and metastasis by increasing DNA 5-methylcytosine (5mC) and suppressing 5-hydroxymethylcytosine (5-hmC) through inhibition of TET-2, resulting in global DNA hypermethylation." (PMID 36344992, 2022). "The malignant tumors with a higher PASS (≥ 4) and/or a GAPP grade of moderately to poorly differentiated type had an increased expression of Nrf2 mRNA and protein expressions, an elevated SUVmax on 18F-FDG-PET, and SDHB gene mutation." (PMID 35300626, 2022). "Several reports have indicated that SDHB plays an important role in controlling cancer metastasis." (PMID 36344992, 2022). "Even patients with SDHB mutation and the only one with the malignant tumor had no further progression of tumors or development." (PMID 35054195, 2021). "Furthermore, a significant proportion of SDHB- and RET-associated malignant tumors also showed an increase in GLS-1 staining compared to benign RET-associated and sporadic tumors." (PMID 32150977, 2020). "In conclusion, we assume that GLS-1 contributes to SDHB-mutant malignant tumor growth and we presume that the evaluation of GLS-1 expression before therapy might yield valuable information for the management of the disease." (PMID 32150977, 2020).
cancer (continued). "Succinate dehydrogenase complex iron sulfur subunit B (SDHB), fumarate hydratase (FH), and the cytosolic and mitochondrial isocitrate dehydrogenase (IDH) isoforms 1 and 2 have been shown to be mutated in various types of cancer." (PMID 32365833, 2020). "This compensation coincided with the upregulation of a CII component (SDHB) in the proteomics analysis and may play an important role in the protection of cancer cells from the antitumor effect of sorafenib." (PMID 31881007, 2019). "Most importantly, over expression of SDHB can inhibit the migration and invasion induced by miR-96-3p, implicating the miR-96-3p/SDHB may play a key role in the process of the cancer and metastasis of the PTC." (PMID 31749660, 2019). "There are researches indicated that SDHB involved in the metastasis of cancers." (PMID 31749660, 2019). "Therefore, it is not fully understood how human cancer cells, which completely ablate SDHB expression, change intracellular metabolism and adapt for survival." (PMID 28423651, 2017). "Somatic SDHB c.136C>T mutation has not been identified in any TCGA sample for these cancers (data release 17 of the International Cancer Genome Consortium22)." (PMID 25898173, 2015). "We previously reported inherited recessive SDHB mutations in association with a paediatric primary mitochondrial phenotype and this case also lacked a history of hereditary cancer." (PMID 26008905, 2015). "Our current data suggested that SDHB play an important role in cancer progression." (PMID 25491408, 2014). "With specific regard to SDHA and SDHB, vitamin E (α-tocopheryl succinat, target: respiratory complex II in mitochondria) and resveratrol (target: respiratory complex V in mitochondria, ATP synthase) were shown to induce apoptosis in cancer cells." (PMID 25048361, 2014). "We found that the level ATP was decreased in SDHB-silenced cancer cells." (PMID 25491408, 2014). "In addition, we present evidence for increased LDHA and SOD2 expression in SDHB-PHEOs/PGLs, proteins that have been proposed as promising therapeutic targets in other cancers." (PMID 22859959, 2012). "Patients with pathogenic mutations in SDHB and FH, for example, have an elevated risk for malignant tumor development, regardless of whether the mutation was inherited or whether it occurred somatically." (PMID 31212687, 2019). "In addition, such drugs would have an advantage in that selection of patients with SDHB mutant cancer could increase the probability of success in the clinical development of the drugs." (PMID 28423651, 2017). "Therefore, increased levels of 3-methoxytyramine, which is a product of dopamine metabolism, could help biochemically identify SDHB or other likely malignant tumours." (PMID 29166454, 2017). "In addition, such drugs would have an advantage in that selection of patients with SDHB-mutant cancer could increase the probability of success in clinical trials." (PMID 28423651, 2017). "Moreover, SDHB was decreased in CoCl2-treated cancer cells accompanied by HIF-1α up-regulation." (PMID 25491408, 2014). "Using the OncoGuide NCC Oncopanel System (114 genes) and FoundationOne CDx Cancer Genomic Profile (324 genes), they identified alterations in KIT (78%), PDGFRA (6%), and SDHB (6%)." (PMID 41355515, 2025). "However, the contribution of glucose-derived carbon sources to aspartate (m + 3) via PC in our SDHB-deficient cancer cells was not as substantial as that reported in their work, which insisted on the importance of PC-dependent aspartate synthesis for SDHB-deficient cancer cell growth." (PMID 28423651, 2017). "For investigation of proliferating cancer cells and its relation to metabolic characteristics, we performed correlation analysis of Ki-67 with GLUT-1, HK 2, LDHA, TKTL1, SDHA, SDHB, and ATP synthase in OSCC." (PMID 25048361, 2014). "The region contains multiple genes with a known or suspected role in cancer including ARID1A, E2F2, NBPF1, PAX7, RUNX3 and SDHB." (PMID 25420937, 2014).
cancer (continued). "More recently, characterization of OXPHOS in cancer was performed by describing succinate dehydrogenase SDHA, SDHB (respiratory complex II in mitochondria), and ATP synthase (respiratory complex V in mitochondria)." (PMID 25048361, 2014). "This is supported by our data showing a significantly correlation of proliferating cancer cells with both glycolysis-related proteins (GLUT-1, TKTL1), and OXPHOS-related enzymes (SDHA, SDHB, ATP synthase)." (PMID 25048361, 2014). "Of the 27 patients who presented with multiple PGLs at the time of their genetic counseling consultation, 24 completed genetic testing and 19 (79.2%) tested positive for an LPV/PV in a hereditary cancer gene, all of which were in PGL/PCC genes (SDHD = 13, SDHB = 4, SDHC = 2)." (PMID 39539798, 2024). "As anticipated, overall SDHA levels were similar among the cell types (quantitative data not shown), but SDHB levels were 1.8-fold lower in cancer compared to adjacent normal tissues." (PMID 37945749, 2023). "Third, from our in silico gene deletion analysis, we identified Sterol O-Acyltransferase 1 (SOAT1), methylmalonyl-CoA mutase (MUT), and isozymes of succinate dehydrogenase (SDHA, SDHB, SDHC, and SDHD) as having a significant effect (p-value < 0.05) in cancer as compared to normal samples." (PMID 33396819, 2020). "The mechanism by which SDHB or SDHD expression is reduced in cancer cells is not entirely clear." (PMID 36344992, 2022). "Although not the case for all cancers, RCC has been regarded as a cancer driven by metabolic disorders due to the abnormal expression of genes that regulate various metabolic pathways, such as FH and SDHB in the Krebs cycle (Linehan, Srinivasan & Schmidt, 2010)." (PMID 32832275, 2020). "We conclude that there is no cancer type in TCGA that harbors an excess of damaging germline variants in DDR or cancer-relevant genes, with the exception of the well-described predisposition syndrome genes BRCA1/2, SDHB, and RET." (PMID 30217226, 2018). "However, it has not yet been fully understood how SDHB-null cancer changes intracellular metabolism and adapts for survival." (PMID 28423651, 2017).